IL6 (interleukin 6)
Diseases named in the same sentence as IL6 in open-access papers (continued):
Sharing a sentence is not in itself a finding about the gene and the disease.
rheumatoid arthritis (continued). "IL-32 induces the production of pro-inflammatory cytokines such as tumor necrosis factor (TNF)-α, IL-1β, IL-6, and IL-8, and IL-32 expression is highly increased in rheumatoid arthritis (RA) patients." (PMID 38675491, 2024). "These inflammatory pathways, particularly those involving the IL-1 family and IL-6, have been shown to be key contributors to the development and progression of rheumatoid arthritis." (PMID 39430588, 2024). "Similar to our data, another CDK7 inhibitor BS-181 also inhibits the expression of IL-6 and the inflammation of rheumatoid arthritis." (PMID 38540292, 2024). "Interleukin-6 (IL-6) correlates with joint erosion in rheumatoid arthritis, stimulating RANKL production and potentially influencing bone resorption, especially in estrogen-deficient conditions." (PMID 38474093, 2024). "For instance, in the serum-transferred K/BxN arthritis model, there was an observed increase in spinal IL-1β mRNA levels, whereas IL-6 levels remained unchanged, even though a trend towards higher IL-6 CSF levels was observed in rheumatoid arthritis patients." (PMID 38419042, 2024). "We herein aimed to critically examine the bioactive components of the medicinal herb Piper sarmentosum Roxb leaf fractionated extract for its potential to inhibit the influx of interleukin-6 (IL-6) in rheumatoid arthritis." (PMID 38576490, 2024). "IL6 targets JAK/STAT signaling, which has been implicated in the pathogenesis of inflammatory and autoimmune diseases including rheumatoid arthritis." (PMID 38111237, 2024). "Clinically, IL-6 and IL-6 receptor antibodies have proven to have great efficacy in conditions that are driven by IL-6 such as rheumatoid arthritis, systemic juvenile arthritis and Castleman’s disease." (PMID 39682161, 2024). "Th17 is also a CD4+ T cell subset induced by IL-6 and TGFβ signaling, and it plays a pivotal role in autoimmune diseases such as psoriasis, rheumatoid arthritis, and multiple sclerosis." (PMID 38751878, 2024). "In joints, IL-6 expression shows a positive correlation with the severe lesions observed in aseptic joint conditions, such as rheumatoid arthritis or osteoarthritis." (PMID 38540033, 2024). "In rheumatoid arthritis, with higher IL-6 levels, attenuated R. bromii was identified by machine learning." (PMID 39882244, 2024). "ELISA consistently demonstrates elevated levels of p75NTR, sortilin, TNFα, interleukin-1β (IL-1β), interleukin-6 (IL-6), and interleukin-10 (IL-10) in the serum of patients with rheumatoid arthritis compared to healthy subjects." (PMID 38785946, 2024). "Circulating levels of IL6 are elevated in a number of inflammatory diseases, including rheumatoid arthritis, systemic lupus erythematosus, and Crohn’s disease." (PMID 38727303, 2024). "According to a research, excessive IL‐6 synthesis in rheumatoid arthritis can activate and multiply inflammatory T cells and B cells, elicit immunological responses, and lead to the formation of autoantibodies, aggravating the condition." (PMID 39479687, 2024). "IL-6 is documented in various inflammatory pathologies, starting with acute gastroenteritis, autoimmune diseases, systemic juvenile idiopathic arthritis, rheumatoid arthritis, inflammatory bowel diseases and colorectal cancer." (PMID 39062898, 2024). "It has been proven that excessive synthesis of IL-6 can trigger diseases, proceeding with autoimmunity, such as rheumatoid arthritis (RA) or indeed MS, where the action of Th17 cells is considered a key cause of disease onset." (PMID 39456713, 2024). "one study found that rheumatoid arthritis patients with low IL-6 levels experienced better outcomes with TCZ, while another study reported the opposite." (PMID 39703501, 2024). "In this context, it is well-known that healing complications occur more frequently in patients with inflammatory disorders, which are often associated with increased circulating pro-inflammatory cytokine levels (including IL-6), such as rheumatoid arthritis." (PMID 39166608, 2024).
rheumatoid arthritis (continued). "MMPs are overexpressed in conditions like rheumatoid arthritis, along with interleukin 1β (IL-1β), interleukin 6 (IL-6), and chemokines." (PMID 39766566, 2024). "Work in a rheumatoid arthritis model showed that ephrin B1 increased tumor necrosis factor alpha (TNFα) and interleukin-6 (IL-6) actions in lymphocytes." (PMID 38501146, 2024). "The current indications for IL-6 inhibitors have expanded from the initial rheumatoid arthritis, to more recent giant cell arteritis, and systemic sclerosis-associated interstitial lung disease." (PMID 39749325, 2024). "The existence of various cytokines (e.g., interleukin (IL)-1, IL-6, and transforming growth factor-β (TGFβ)) in the synovial tissue plays a pivotal role in rheumatoid arthritis pathogenesis by promoting the differentiation and proliferation of T cells." (PMID 39684587, 2024). "IL-6 plays important roles in immune homeostasis and the pathogenesis of autoimmune diseases, such as rheumatoid arthritis (RA) and systemic lupus erythematosus (SLE), as well as in infectious diseases like sepsis and SARS-CoV2 pneumonia." (PMID 39065221, 2024). "The study excluded autoimmune conditions with elevated IL-6, such as rheumatoid arthritis, systemic lupus erythematous, ankylosing spondylitis, psoriasis, and Crohn's disease." (PMID 39280507, 2024). "IL-6, an important factor in B-cell maturation and autoantibody production, induces articular and systemic symptoms of rheumatoid arthritis." (PMID 38339007, 2024). "For example, in rheumatoid arthritis, a monovalent gold compound aurothioglucose inhibited IL-6 and IL-8 induction." (PMID 38082190, 2024). "The potential core targets for Mugua treatment of rheumatoid arthritis are IL-6, TNF, IL-1β, and IL-10." (PMID 39705460, 2024). "The Il-6–IL-6R axis seems to be responsible for inflammatory process maintenance and the progression of inflammatory diseases, such as rheumatoid arthritis." (PMID 39062898, 2024). "A previous study reported that in Rheumatoid arthritis, IL-6 is a key pro-inflammatory cytokine induced by sphingosine-1-phosphate through the activation of PI3K, MEK/ERK, and NF-κB signaling cascades." (PMID 39291284, 2024). "Tocilizumab is a monoclonal antibody against IL-6R including sIL-6R and IL-6/sIL-6R complex and it has been approved for the treatment of rheumatoid arthritis and cytokine release syndrome." (PMID 38541674, 2024). "Emerging therapies, such as anti-IL-6 treatments that have shown effectiveness in reducing inflammation in conditions like rheumatoid arthritis, hold promise for CVD management but require further clinical validation." (PMID 39595090, 2024). "The use of IL-6 or IL-6r inhibitors, such as sarilumab or tocilizumab, is approved for the treatment of immune related toxicities, autoimmune diseases such as arthritis rheumatoid, and of cytokine release syndrome from CAR-T or Tebentafusp." (PMID 38443899, 2024). "IL-6 is a well-recognized activator of cytokines within the pathway of JAK/STAT, and raised concentrations of IL-6 have been identified in chronic inflammatory disorders, including rheumatoid arthritis and OA." (PMID 38812033, 2024). "Clazakizumab and siltuximab directly target the site I of IL-6 for interfering the formation of IL-6 and IL-6R complex, and have been approved for the effectiveness in the treatment of rheumatoid arthritis (RA) and Castleman’s disease in clinical trials." (PMID 38890694, 2024). "IL-6 is an inflammatory cytokine that plays a major role in Rheumatoid arthritis (RA) pathogenesis and is commonly treated as a leading cause of CRS." (PMID 39445021, 2024). "Treatment of autoimmune diseases such as rheumatoid arthritis conventionally relies on anti-IL-6 antibodies." (PMID 39201432, 2024). "Background/Objectives: This study aimed to investigate the association of IL-6 with steatotic liver disease (SLD) and liver fibrosis (LF) in rheumatoid arthritis (RA) patients at a rheumatology center in Cartagena de Indias, Colombia." (PMID 39766906, 2024).
rheumatoid arthritis (continued). "Although IL-6 is a pro-inflammatory cytokine and its levels are very high in processes involving an inflammatory response (including autoimmune diseases like rheumatoid arthritis), IL-6 can also exhibit anti-inflammatory effects via the membrane-bound IL-6R." (PMID 39007140, 2024). "Various inflammatory or immune-mediated diseases, such as rheumatoid arthritis, multiple sclerosis, and cancer, were previously characterized by impaired IL-6 activity." (PMID 38397895, 2024). "The physiological concentration of IL-6 in normal human serum is relatively low, about 1–5 pg/mL, but in various inflammatory conditions (such as rheumatoid arthritis and meningitis), IL-6 levels increase rapidly." (PMID 39451670, 2024). "IL-6 activity in rheumatoid arthritis and Castleman ́s disease can be efficiently inhibited by antibodies in contrast to the situation in cancer." (PMID 39518029, 2024). "At baseline, the IL-6 levels (median 4.1 pg/mL) in the three patients were below what has previously been described in patients with rheumatoid arthritis (~ 50 pg/mL)." (PMID 37831074, 2023). "Excessive JAK/STAT stimulation by cytokines such as IL-1, IL-6, IL-15, TNF-α, and IFN has been associated with rheumatoid arthritis (RA), multiple sclerosis, inflammatory bowel disease, and periodontal disease, to name a few." (PMID 37373437, 2023). "Patients with systemic inflammatory disorders, such as rheumatoid arthritis, and a concurrent Zn shortage have been demonstrated to have higher levels of IL-1α, IL-1β, and IL-6 expression compared to those who consume more Zn." (PMID 37946846, 2023). "Anti-IL-6 therapy is usually used as an immunosuppressant in rheumatoid arthritis and its use requires monitoring of liver function." (PMID 37445553, 2023). "Adult subjects with rheumatoid arthritis, on the other hand, have shown to have lower levels of multiple LPCs, which were further correlated with interleukin-6 and disease activity indices." (PMID 36915680, 2023). "IL-1β, IL-6, and TNF are three cytokines implicated in PASC and other inflammatory diseases such as rheumatoid arthritis, with IL-1 also contributing to inflammation in MS." (PMID 37112929, 2023). "Rheumatoid arthritis (RA) is an autoimmune inflammatory disease associated with rheumatoid factors and anti-cyclocitrullinate peptide antibodies, which involve inflammatory cytokines, such as TNFα, IL-1, and IL-6." (PMID 36518035, 2023). "This study was aimed at comparing the incidence rates (IRs) of malignancies and MACEs in patients with rheumatoid arthritis (RA) treated using interleukin-6 (IL-6) inhibitors (IL-6is) or JAKis." (PMID 37868999, 2023). "In patients with rheumatoid arthritis, characterized by a substantial volume of IL-6 in both synovial fluid and serum, tocilizumab selectively binds to this cytokine, consequently alleviating the symptomatic manifestations of the disease." (PMID 37986199, 2023). "TNF-alpha and IL-6 are key pathogens involved in immune-mediated bone diseases, such as postmenopausal osteoporosis and rheumatoid arthritis." (PMID 37246213, 2023). "Elevated levels of IL-6 and its receptors are commonly observed in patients with rheumatoid arthritis." (PMID 38032288, 2023). "In rheumatoid arthritis, IL-6 plays a central role in theinflammatory cascade, contributing to joint inflammation and destruction." (PMID 39077574, 2023). "In fact, in rheumatoid arthritis, urinary IL-6 levels correlated positively with its serum levels as well as serum C-reactive protein, Disease Activity Score 28 and white blood cell count." (PMID 37189804, 2023). "Patients with rheumatoid arthritis had ~4-fold higher levels of urinary IL-6 in comparison to healthy controls." (PMID 37189804, 2023). "gp130F759/F759 (F759) mice are a mouse model that spontaneously develops rheumatoid arthritis in which joint inflammation is amplified by the IL-6 amplifier." (PMID 37936169, 2023).
rheumatoid arthritis (continued). "IL-6 is crucial to the pathogenesis of rheumatoid arthritis–inducing osteoporosis at local and peripheral levels." (PMID 36982692, 2023). "In patients for whom biological therapy has failed, the use of drugs like mavrilimumab (an antibody against GM-CSF), rituximab (an Anti CD20 antibody), and tocilizumab (rheumatoid arthritis is a multifactorial disease that blocks IL6) were encouraging." (PMID 38003865, 2023). "It is reported that caffeic acid alleviates inflammatory response in rheumatoid arthritis by repressing IL-6 and TNF-α." (PMID 37372012, 2023). "Treatment of fibroblast-like synoviocytes (FLS) isolated from rheumatoid arthritis (RA) patients with agonists of α7 nAChR reduced the levels of the pro-inflammatory cytokines IL-6 and IL-8." (PMID 37893130, 2023). "Yoshida Y reported that elevated IL-6 levels are present in the synovial and blood of rheumatoid arthritis patients." (PMID 37241088, 2023). "For this reason, blockade of IL-6 is used as a treatment for rheumatoid arthritis and is in clinical trials for other inflammatory conditions, including cancer." (PMID 37397366, 2023). "These cytokines are already associated with diseases such as rheumatoid arthritis and psoriasis (TNF), Castleman disease and rheumatoid arthritis (IL-6), and type 2 diabetes, smoldering myeloma, urate crystal arthritis, and osteoarthritis among others (IL-1β)." (PMID 37112929, 2023). "The serum level of oxidative stress was lower in rheumatoid arthritis patients treated with Tocilizumab, suggesting IL-6 inhibition therapy reduces joint damage and vascular degeneration." (PMID 37357527, 2023). "IL-6 and IL-17A can promote articular cartilage and bone damage; the concentration of IP-10 and IL-12 is closely related to the pathogenesis of rheumatoid arthritis." (PMID 37537628, 2023). "It is also used to treat rheumatoid arthritis (RA) and this was attributed to its anti-inflammatory property in reducing key proinflammatory cytokines of RA – interleukin-6 (IL-6) and TNF-α, matrix metalloproteinases (MMPs) and prostaglandin E2." (PMID 36911685, 2023). "Treatment with 20-hydroxyecdisone reduced TNF-α, IL-1β, IL-6 and NF-κB in rat serum in a rheumatoid arthritis model." (PMID 37687297, 2023). "Another piece of evidence that came from a recent study showed that VD3 and IL-6 blockade (Tocilizumab) synergistically regulate rheumatoid arthritis by suppressing IL-17." (PMID 36904187, 2023). "Reduction in tumor necrosis factor (αTNF) and interleukin-6 (IL-6) activities is a widely utilized strategy for the treatment of rheumatoid arthritis (RA) with a high success rate." (PMID 36836953, 2023). "A study has reported that Sema4A can aggravate the pathological progression of rheumatoid arthritis by synergistically regulating the generation of IL-6 with lipopolysaccharide." (PMID 37901456, 2023). "IL-6 release has been shown to be important in many diseases, such as Crohn’s disease and rheumatoid arthritis, and studies have suggested that it also plays an important role in inflammatory reactions in spinal cord injury and acts as a neurotoxic agent." (PMID 37111284, 2023). "It is known that serum CRP, which is induced by IL-6, is less likely to be elevated in patients with rheumatoid arthritis who are being treated with anti-IL-6 receptor antibody preparations." (PMID 38002777, 2023). "Among SNPs used in the instrument for IL-6, we found a few associations with potential confounders such as CVD, eczema and rheumatoid arthritis." (PMID 37217205, 2023). "Its mechanism of action in rheumatoid arthritis, akin to the pathophysiology of COVID-19, centers on its ability to mitigate the impact of elevated interleukin-6 (IL-6) levels." (PMID 37986199, 2023). "Monoclonal antibodies against IL-6 have been applied in the treatment of rheumatoid arthritis, indicating its important role in systemic inflammation or autoimmune diseases." (PMID 36902060, 2023).
rheumatoid arthritis (continued). "Several studies reported that the decrease in IL-6 production leads to reduced inflammation in rheumatoid arthritis, asthma, and atherosclerosis." (PMID 37629511, 2023). "The model in this study used IL-6 at 10 ng/mL for maximum effect, which is higher than what is found in inflammatory conditions, (e.g., 0.5 ng/mL in rheumatoid arthritis synovial fluid)." (PMID 36942294, 2023). "Metformin has been shown to inhibit expression of IL-6 and TNF-α in HaCaT keratinocytes, and to reduce IL-6 and IL-8 in rheumatoid arthritis synovial explants." (PMID 37108132, 2023). "One physician described a patient with rheumatoid arthritis.“...very complicated rheumatoid arthritis patient that tried all the TNF blockers...she tried Il-6, she failed." (PMID 37454024, 2023). "Tocilizumab is a humanised monoclonal antibody targeting the IL-6 receptor to inhibit IL-6 signalling, licensed in the UK for treatment of rheumatoid arthritis." (PMID 36963796, 2023). "We report the case of an 81-year-old woman with rheumatoid arthritis treated with steroids and an IL-6 inhibitor who was diagnosed with scedosporiosis of the upper limb." (PMID 37367619, 2023). "Conventional (such as methotrexate and sulfasalazine) and biological (TNF and IL-6 inhibitors) DMARDs have been the mainstay for treating patients with rheumatoid arthritis." (PMID 37373437, 2023). "The present study was designed to investigate further the influence of IL-6 in combination with sIL-6R and sarilumab on osteoblasts derived from patients with rheumatoid arthritis." (PMID 37280473, 2023). "There is a known correlation between the level of IL-6 and the severity of such autoimmune diseases as rheumatoid arthritis (RA), systemic lupus erythematosus (SLE), and Crohn’s disease." (PMID 37894997, 2023). "Recently, a preclinical study showed that administering neutral electrolyzed saline in a rheumatoid arthritis model reduced IL-6 levels in a dose-dependent manner." (PMID 36837598, 2023). "Supplementation of vitamin B6 was shown to suppress TNF-α and IL-6 levels in patients with rheumatoid arthritis." (PMID 37761018, 2023). "IL-6 antagonists have been described as therapeutic options in various rheumatic diseases such as rheumatoid arthritis and juvenile idiopathic arthritis." (PMID 37733154, 2023). "The IL-6 levels of patients with rheumatoid arthritis (RA) are measured with an interdigitated aptasensor, and the sensor can provide a linear range from 0.021 pg/mL (1 fM) to 2100 pg/mL (100 pM)." (PMID 36679421, 2023). "The Pad4 gene has been reported to be dependent on IL-6 in neutrophils extracted from a rheumatoid arthritis mouse model, and it is essential for NET formation against bacterial infection in neutrophils." (PMID 37189826, 2023). "Infliximab and Etanercept (TNF-α inhibitors) and Tocilizumab (IL-6 inhibitor) are currently prescribed to treat rheumatoid arthritis." (PMID 37108210, 2023). "There are also reports of IL-6-gp130–mediated signaling activity in rheumatoid arthritis, leading to JAK1 and STAT3 activity." (PMID 38139151, 2023). "Clinical studies have established a correlation between elevated levels of IL-6 and heightened pain in individuals suffering from MD, such as rheumatoid arthritis and fibromyalgia." (PMID 37218835, 2023). "TNF-α, NF-, IL-1, and IL-6 are known key regulators in the pathogenesis of rheumatoid arthritis and other inflammatory diseases, and chloroquine has been shown to inhibit IL-1, IL-6, and TNF- production in human monocytes stimulated with lipopolysaccharide." (PMID 36677853, 2023). "In contrast to rheumatoid arthritis, where urinary and serum IL-6 levels correlated (see Section 2.6.1), urinary and serum IL-6 concentrations did not correlate in children with urinary tract infections." (PMID 37189804, 2023). "Monoclonal antibodies directed against IL-6, including tocilizumab, sarilumab, and others, have been suggested for rheumatoid arthritis treatment." (PMID 37627815, 2023).